BRCA2 (BRCA2 DNA repair associated)
Diseases named in the same sentence as BRCA2 in open-access papers (continued):
Sharing a sentence is not in itself a finding about the gene and the disease.
tumor (continued). "Upregulation of interferon and related genes was also observed in human BRCA2-mutant tumour samples." (PMID 37626143, 2023). "P/LP variants identified in tumor-only sequencing of GISTs were almost exclusively germline in certain genes, such as BRCA1, BRCA2 (4/4 variants), and SDHB (10/11 variants)." (PMID 36593350, 2023). "WGS detected a tumour mutational burden (TMB) of 2.9 mutations per Mega base; LOH of 0.48; homozygous deletion of BRCA2; and a dominant COSMIC mutational signature 3, indicating that this uLMS was HRD." (PMID 37143137, 2023). "For the 4 patients that experienced clinical benefit with PFS > 6 months, the tumor types were ampullary, colon, pancreatic, and ovarian and only 1 of 4 patients (ovarian) had a mutation identified in an HRD gene (BRCA2)." (PMID 37377610, 2023). "We first evidenced a larger number of circRNAs in BRCA1 than in BRCA2, in accordance with RJunBase, with a similar qualitative repertoire between normal and tumor tissues." (PMID 37046838, 2023). "In a previous gene mutation analysis conducted in tumor tissue alone, more than 80% of BRCA1 and BRCA2 variants detected were reported to be of germline origin." (PMID 36494460, 2023). "The two main ones include: (i) sequencing of key DNA repair genes, such as BRCA1, BRCA2 or PALB2, to identify pathogenic variants, both germline and somatic, (ii) quantifying HRD-associated genomic features in tumor DNA, with often these two combined." (PMID 36805632, 2023). "Firstly, it was questioned which genes the tumor DNA test should cover in addition to BRCA1 and BRCA2, since the germline test panel includes more OC risk genes." (PMID 35570228, 2023). "In these clinical scenarios, the panellists considered tumour genetic testing inappropriate and germline testing appropriate only if a BRCA2 germline (L)PV was present in the family." (PMID 36874601, 2023). "This tumor also showed activity of SBS3 and ID6 from mutational signature analysis and a low expression of the BRCA2 gene." (PMID 36702933, 2023). "BRCA1 and BRCA2 are required for mammalian development, and they function as tumor suppressors to support the maintenance of genomic integrity." (PMID 37813891, 2023). "This approach provides an opportunity to target tumors with mutations in tumor suppressor genes such as BRCA1, BRCA2, and RAD51, where loss of function results in the tumorigenic consequences of deficient homologous recombination." (PMID 37628794, 2023). "This study analyzing BRCA1, BRCA2, and PALB2 mutations through tumor-targeted sequencing boosts several notable strengths." (PMID 38098088, 2023). "We have characterized novel BRCA1 and BRCA2 circular RNAs and, for the first time, described a disequilibrium in circRNA/mRNA levels between tumor and normal breast tissues." (PMID 37046838, 2023). "The only two BRCA1/2 pathogenic variants detected in patients diagnosed at ≥80 years old were small sequencing variants that were detected in tumour DNA (BRCA1:c.68_69del and BRCA2:c.4478_4481del)." (PMID 38201604, 2023). "The only patient diagnosed with a germline BRCA1/2 pathogenic variant aged ≥80 had a small deletion (four base pairs in size) in BRCA2 that was detected first in tumour DNA and then subsequently in germline DNA." (PMID 36765687, 2023). "The BRCA2 tumour suppressor gene is essential for homologous recombination (HR) repair and replication fork stability maintenance." (PMID 37446144, 2023). "In patients with de novo mHSPC, presence of a BRCA2 tumour (L)PV would influence the choice of upfront treatment in only a minority of panellists." (PMID 36874601, 2023). "Human genes called BRCA1 and BRCA2 translate into tumor suppressors, which contribute to DNA repair as well as aid in preserving the integrity of the genomic information." (PMID 36971312, 2023).
tumor (continued). "The C BRCA2 rs15869 allele and the C CCND1 rs7177 allele were statistically likely to be associated with a high histological degree of tumor proliferation, eating high atypia, and invasion rates." (PMID 38156855, 2023). "Two additional pathogenic HRD gene alterations (both homozygous deletions in BRCA2) were detected by tumour panel NGS testing (uLMS438, uLMS683)." (PMID 37143137, 2023). "Down-regulated genes belong to the class of oncogenes (Akt1, Ccnd1, Myb, and Src) and tumor suppressors (Brca1, Brca2, and Mlh1)." (PMID 37297299, 2023). "Out of 157 patients, who had resulted negative for PVs at tumour testing, only one (0.6%) was positive for a BRCA2 duplication both in the tumour and germline." (PMID 37179432, 2023). "Pathogenic mutations in BRCA1 or BRCA2 genes were detected in 2% and alterations in other HRR-related genes in 8% of evaluated tumor samples." (PMID 38201431, 2023). "By interacting with the BRCA2 protein, the tumor suppressor partner and localizer ofBRCA2 (PALB2) plays a critical part in repairing DNA damage and preventing thegrowth of tumors." (PMID 39430039, 2023). "The Brca1−/− cell line expressed various monocyte recruitment factors in vitro and the Brca1−/− and Brca2−/− tumours had evidence of antigen processing expression in their bulk RNA profiles." (PMID 37957414, 2023). "Previous studies have shown that cediranib is a highly effective VEGFR (KDR) inhibitor and that cediranib targets BRCA2/RAD51 in tumor cells." (PMID 37355516, 2023). "BRCA1 and BRCA2 as tumour suppression genes are crucial in the DNA repair process by homologous recombination, which plays an essential role in chromosome integrity." (PMID 37644384, 2023). "A 42-year-old woman diagnosed with stage IV BRCA2 germline mutant AC underwent platinum-based first line treatment achieving major tumor response but also life-threatening toxicity." (PMID 36998040, 2023). "BRCA2 carriers and young patients had larger average tumor sizes and a higher proportion of positive lymph nodes, tumor grade 3, and high Ki-67 than the older patients." (PMID 38036573, 2023). "Secondly, we have demonstrated a disequilibrium for BRCA1 and BRCA2 in the circRNA/mRNA ratio between the tumor and normal breast tissues." (PMID 37046838, 2023). "BRCA1 and BRCA2 act as tumor suppressor genes as they are key regulators of DNA repair through homologous recombination." (PMID 38203374, 2023). "Based on the sensitivity to platinum agents in BRCA2 mutation-positive tumors, DAC-Tam therapy (Dacarbazine, Nimustine, Cisplatin, and Tamoxifen) was administrated and showed tumor size reduction." (PMID 37868454, 2023). "SEALigHTS deciphered the BRCA1 and BRCA2 backsplicing landscape in normal and tumor breast tissues and identified not only the already described circRNAs but also 10 and 5 novel ones for BRCA1 and BRCA2, respectively." (PMID 37046838, 2023). "This resulted in a very strong separation of tumours with all BRCA1 and BRCA2 positive tumours having a HRDetect score of > 0.99." (PMID 37316882, 2023). "BRCA1 and BRCA2 are often mentioned together, partly owing to their tumor-suppressor activities and roles in HR repair." (PMID 37209095, 2023). "The three germline BRCA1/2 variants missed using our in-house tumour BRCA1/2 assay included BRCA1 Exon 13 duplication, BRCA2 Exon 1–2 deletion and BRCA2 Exon 14–16 deletion." (PMID 36765687, 2023). "BRCA1 and BRCA2 mutation status and TMB were analyzed in tumor DNA using next-generation sequencing." (PMID 37446361, 2023). "In this research set, ratios of BRCA1 and BRCA2 circRNAs/mRNAs were significantly lower in the tumor breast tissue compared to normal tissue (p = 1.6 × 10−9 and p = 4.4 × 10−5 for BRCA1 and BRCA2, respectively)." (PMID 37046838, 2023). "Emerging evidence suggests Brca2-mutant tumours activating immune and interferon-related signalling programmes and respond to checkpoint blockade immunotherapies." (PMID 37626143, 2023).
tumor (continued). "Loss of BRCA1 or BRCA2 function in normal cells leads to growth defects that, combined with a subsequent loss of other DDR mediators, promote tumour development." (PMID 37644384, 2023). "Among non-BRCA1/BRCA2 tumours, the RNA classifier identified 5/23 (22%) tumours with BRCAness compared to HRDetect predicting 3/23 (13%) tumours as having BRCAness." (PMID 37316882, 2023). "Tumor characterization by HRD score testing identifies possible gene mutations (at the level of the BRCA1 and BRCA2 genes in the tumor tissue) and reveals genomic instability through LOH, LST, and TAI (collateral damage)." (PMID 37296748, 2023). "If a patient was identified with any P/LP variants of BRCA1, BRCA2, or PALB2 within the tumor, clinical germline testing (CGT) would be performed." (PMID 38098088, 2023). "In our cohort, which included 203 HGOC women who had not undergone prior germline analyses, 45 patients showed BRCA1/2 pathogenic or likely pathogenic variants (henceforth termed as PVs) at tumour testing (31 BRCA1, 14 BRCA2)." (PMID 37179432, 2023). "The only germline PV reported in a patient aged ≥80 was detected in germline and tumour DNA (BRCA2 c.4478_4481del)." (PMID 36765687, 2023). "BRCA1 and BRCA2, two tumor suppressor genes that interact with G4 structures, participate in homologous recombination and thus allow the repair of DNA DSBs." (PMID 36770824, 2023). "Two patients had a tumor with a BRCA1 mutation, one had BRCA1 and FANCA mutations, one had a PALB2 mutation, one had a BRCA1 VUS, and one had a BRCA2 VUS." (PMID 37173992, 2023). "Between 11 April 2021 and 11 October 2023, 382 patients were successfully tested for tumour BRCA1 and BRCA2 variants." (PMID 38201604, 2023). "The remaining BRCA2 wild-type (WT) tumours (n = 568; 88.1%) were used as a background set for training the predictive models." (PMID 36883553, 2023). "Another Polθ inhibitor, ART558, also exhibited synthetic lethality in BRCA1- or BRCA2-mutant tumor cells and enhanced the cytotoxicity of PARPi29." (PMID 37429899, 2023). "The tumor suppressor BRCA2 participates in DNA double-strand break repair by RAD51-dependent homologous recombination and protects stressed DNA replication forks from nucleolytic attack." (PMID 36702902, 2023). "Clinical benefit was greatest amongst patients with BRCA2 and ATM mutations, including durable objective tumour responses, with minimal toxicities attributable to combining olaparib with durvalumab." (PMID 37365284, 2023). "Among the BC patients positive for BRCA1-, three (100%) had a triple-negative BC whereas, among those positive for BRCA2- tumours, two were triple-negative BC (40%), one was Luminal B/HER2- (20%) and two were Luminal B/HER2+ (40%)." (PMID 35886069, 2022). "Of note, the 1 hetloss was considered as an alteration whereas the 1 amplification was considered as wild-type, since BRCA2 is a tumor-suppressor gene." (PMID 36362213, 2022). "These cells harbor mutations in BRCA2, PIK3CA, PTEN, and ARID1A genes, among others, associated with tumor initiation." (PMID 36438565, 2022). "Thirty-six tumour-related genes including ALK, AR, BRCA2, FANCD2 and CBL were found to be mutated in all the three disease groups." (PMID 36686473, 2022). "BRCA2 has been primarily associated with HRD and with the tumor suppressive function of this repair process." (PMID 35626055, 2022). "In PC, BRCA1 co-regulates the AR activity mediating tumor progression, while BRCA2 limits the metastatic potential of PC by MMP9 downregulation and inhibition of the PI3K/AKT and MAP/ERK pathways (which also regulate PD-L1 expression)." (PMID 35203446, 2022).
tumor (continued). "Whilst the tumour characteristics tested were significantly associated with BRCA1 status, these were also associated with BRCA2 status, with the exception of ER, PR, HR, and TNBC." (PMID 35143328, 2022). "BRCA1 and BRCA2 are canonical tumor suppressor genes involved in DNA damage repair through the HRR pathway." (PMID 35163129, 2022). "When comparing percent genome wide-LOH scores between BRCA1 and BRCA2 mutated tumours in both breast and ovarian cohorts, the scores were higher for BRCA1 than BRCA2 in ovarian (28 vs. 20, P < 0.001), and in breast (25 vs. 22, P < 0.001)." (PMID 34979999, 2022). "CX-5461 was found to be synthetically lethal in BRCA2 and BRCA1-deficient tumor models both in vitro and in vivo, independently of RNA polymerase 1 inhibition." (PMID 35750695, 2022). "Other important tumor-suppressing genes that, once mutated, result in the occurrence of breast cancer include BRCA1 and BRCA2." (PMID 36233156, 2022). "Our study found that tumor samples in the high-risk group expressed higher levels of BRCA1 and BRCA2 but lower levels of CTLA4 and PDCD1." (PMID 36704358, 2022). "In TOPARP-B, patients with tumours harbouring homozygous BRCA2 deletions demonstrated a superior median rPFS of 16.4 months vs. 5.6 months for germline BRCA1/2 mutations and 8.2 months for BRCA1/2 somatic mutations." (PMID 36497408, 2022). "It proved to be a viable and cost-effective approach for determining BRCA2 protein expression in tumor samples for this study, as similarly reported by other studies, as well as for determining MAGEC3 protein expression." (PMID 36230652, 2022). "An Italian multicenter study evaluating 382 male patients with BCs, including 50 BRCA carriers, reported that MBCs in BRCA2 carriers showed a statistically higher tumor grade, PR negativity, and HER2 positivity." (PMID 35454911, 2022). "A second deletion c.3509_3547del was found on tumor analysis, which restored the reading frame and BRCA2 function." (PMID 36294734, 2022). "PARP inhibitors (PARPi) as single agents show promise in tumor treatment through the synthetic lethality they induce in cells with defects in BRCA1/BRCA2 and other components of the HR repair pathway." (PMID 36361678, 2022). "Taken together, these results confirm that the interaction of BRCA2 with telomere G4 is innate to its tumor suppressor activity." (PMID 35697743, 2022). "Among the 60 patients’ USC, 22 (36.7%) carried tumor HRR gene mutations (tHRRmt), with ATM, BRCA1, and BRCA2 being the most frequently mutated genes." (PMID 36428992, 2022). "Consistent with in vitro results, neither pyridostatin nor its combination with NU‐7441 and/or paclitaxel suppressed growth of BRCA2+/+ tumours or had an impact on mouse survival." (PMID 35107878, 2022). "Several studies showed that hyperthermia has been shown to degrade BRCA2, and produced the impairment of DNA repair in tumor cells with increasing the sensitivity to platinum chemotherapy." (PMID 35965567, 2022). "For example, BRCA2 mutant tumour cell lines that become PARPi resistant after long term in vitro PARPi exposure develop reversion mutations (Glossary), i.e. secondary mutations in BRCA2 that compensate for the original pathogenic mutation." (PMID 35567571, 2022). "BRCA1 and BRCA2 are tumour suppressor genes that play a critical role in maintaining genomic stability via the DNA repair mechanism." (PMID 35729312, 2022). "Median overall survival was nearly 3 years shorter for patients whose tumor(s) expressed BRCA2-001/Short (87 months, 95% CI 71.2–121) compared to those whose tumors did not (121 months, 95% CI 100.0–159)." (PMID 36344544, 2022).
tumor (continued). "They showed that defects in BRCA2 and ATM were strongly associated with poor time to progression independently of clinical prognostic factors and circulating tumor DNA abundance (p < 0.001)." (PMID 35448200, 2022). "BRCA1 and BRCA2 are known as tumor-suppressor genes that function to limit inappropriate cell growth and signal cell death when needed." (PMID 35626055, 2022). "The PTVs in BRCA2, CHEK2, and PALB2 were associated with larger tumor size, lymph node involvement, and higher stage at diagnosis (eFigure 1 in Supplement 1)." (PMID 35084436, 2022). "BRCA1 and BRCA2 are the most recognized tumor-suppressor genes involved in double-strand DNA break repair through the homologous recombination (HR) system." (PMID 35740616, 2022). "Among the ARGs in the risk model, BRCA1 and BRCA2 have been confirmed occurred mutation in TNBC, and were correlated with higher tumor grade and earlier age at menarche." (PMID 35297220, 2022). "NG tumor samples not only possessed comparable rates of gene-level variation [BRCA1 (100%), BARD1 (41%), and BRCA2 (18%)] but also showed comparable variant frequencies." (PMID 36922933, 2022). "A more recent study in 2022 was able to detect both cytoplasmic and nuclear BRCA2 protein expression in GC tumor tissues." (PMID 36497436, 2022). "Two copies of BRCA2 get inactivated subsequently, forming a driving factor for the inactivation of the tumor-suppressor gene and promoting neoplasia." (PMID 35912179, 2022). "With respect to tumor testing, 25 (66%) patients had a BRCA1 mutation and 13 (34%) patients had a BRCA2 mutation (34%)." (PMID 36143252, 2022). "In the course of our in vivo experiments using BRCA2‐deficient DLD1 and HCT116 cell‐derived xenografts we observed that, in spite of initial inhibition, tumours treated with pyridostatin resumed growth at the end of the treatment." (PMID 35107878, 2022). "The unique mode of BRCA2 interaction with telomere G4 is essential for its tumor suppressor activity." (PMID 35697743, 2022). "When comparing HRD-LOH scores between BRCA1 and BRCA2 mutated tumours in both breast and ovarian cohorts, an analysis not performed in the smaller TCGA dataset, the scores were slightly higher for BRCA1 compared with BRCA2 for both tumour types." (PMID 34979999, 2022). "Here, the authors sequence primary and recurrent tumours of BRCA1/2 mutation carriers, finding PARP1 amplifications, differential BRCA2 isoform usage, and discordant loss of heterozygosity that are associated with recurrence." (PMID 36344544, 2022). "Tumor cells with deficiency of HRR genes, especially BRCA1 and BRCA2, are sensitive to PARPi through the mechanism of synthetic lethality." (PMID 35241075, 2022). "When stratified by BRCA1/2 mutation, a similar OS was seen for the different tumor sizes, except for pT1b (97.4% 10-year OS in BRCA1 vs 82.8% in BRCA2,p = 0.049)." (PMID 35507134, 2022). "of the very same guidelines, it is stated that “Somatic tumor testing for BRCA1 and BRCA2 pathogenic or likely pathogenic variants should be performed in women who do not carry a germline pathogenic or likely pathogenic BRCA1/2 variant”." (PMID 35326583, 2022). "A pathogenic variant was detected in 41.1% (60/146) of tumours tested, with 68.3% (41/60) having either a BRCA1 or BRCA2 variant (n = 36), or BRCA1/2 plus a second variant (n = 5), and 31.2% (19/60) carrying a pathogenic variant in another HCP gene." (PMID 36011309, 2022). "Unexpectedly, however, when used in combination, olaparib and TRAIL showed considerable synergistic activity in all the cell lines tested independently of the BRCA2 gene status in cell lines from both tumor entities." (PMID 36358659, 2022). "Tumours with BRCA1 or BRCA2 alterations were more sensitive to olaparib as compared to those with alterations in any other DDR gene." (PMID 36010882, 2022).